LCE3D (late cornified envelope 3D)
Description:
Precursors of the cornified envelope of the stratum corneum.
Synonyms: LEP16; SPRL6A; SPRL6B
Tractability: No criterion of Open Targets' tractability assessment is met for any kind of drug.
Gene: Protein-coding gene on chromosome 1 (152,579,381 to 152,580,516, reverse strand). Ensembl gene ENSG00000163202.
Pathways (Reactome):
Developmental Biology: Formation of the cornified envelope
Gene Ontology:
Molecular function: protein binding
Biological process: epidermis development
Cellular component: cytosol
Genetic constraint (gnomAD): Missense variants: 81 observed, 86.49 expected, observed/expected ratio (o/e) 0.94, 90% interval 0.78 to 1.13. Synonymous variants: 31 observed, 31.75 expected, observed/expected ratio (o/e) 0.98, 90% interval 0.73 to 1.32.
Homologues: Orthologues: chimpanzee LCE3D (98% identical). Paralogues in human: LCE3E (96% identical), LCE3C (85% identical), LCE3B (82% identical), LCE3A (78% identical), LCE2C (66% identical), LCE2D (65% identical), LCE2A (64% identical), LCE2B (64% identical), LCE5A (63% identical), LCE1E (61% identical), LCE1F (60% identical), LCE1D (57% identical), and 8 more.
Diseases named in the same sentence as LCE3D in open-access papers:
LCE3D is named in the same sentence as 12 diseases in open-access papers, as found by Europe PMC text mining. Sharing a sentence is not in itself a finding about the gene and the disease. The quoted sentences say what the papers report.
psoriasis (6 papers, 2013 to 2023). An autoimmune condition characterized by red, well-delineated plaques with silvery scales that are usually on the extensor surfaces and scalp. "Previous studies have reported a strong association between the severity of psoriasis and the Lce3a and Lce3d locus." (PMID 37465147, 2023). "These genes include genes that are well known to be involved in psoriasis, including LCE3D, LCE3E, SERPINB4, and S100A7A, genes involved in activation and proliferation of keratinocytes, modulation of host immune response, and antimicrobial defense." (PMID 30054515, 2018). "Nevertheless, 7 of the PP-increased DEGs were associated with psoriasis susceptibility loci (LCE3D, IFIH1, GRHL3, IL12B, PRSS53, REL and NOS2), and 1 PP-decreased DEG was near a psoriasis susceptibility locus (SDC4)." (PMID 24260178, 2013). "In psoriasis patients, the majority of whom harbor genomic deletion of LCE3B and LCE3C (LCE3C_LCE3B-del), we propose that certain dietary analogues of 1,25D activate the expression of residual LCE3A/LCE3D/LCE3E genes to compensate for the loss of LCE3B/LCE3C in the deletant genotype." (PMID 29401702, 2018).
atopic dermatitis (1 paper, 2022). "In addition, late cornified envelope protein 3D (LCE3D), one of hub genes we have found, is also a specific development associated gene, which participated in the formation of stratum corneum, and was associated with psoriasis vulgaris and atopic dermatitis." (PMID 35256894, 2022).
Insulin resistance (1 paper, 2011). Increased resistance towards insulin, that is, diminished effectiveness of insulin in reducing blood glucose levels. "In future it has to be validated if the other most differentially regulated genes between both tissues such as: SGCD, LCE3D, EREG, NDP and CXCL9, FSTL3, PDZK1IP1 could be used as biomarkers related to insulin resistance of adipose or liver tissues respectively." (PMID 21978410, 2011).
keratoderma (1 paper, 2023). "Specifically, LCE3D was also found to be upregulated in the other diseases with keratoderma: Pachyonychia Congenita and Curth-Macklin ichthyosis." (PMID 37298411, 2023).
LCE3D also shares sentences with these, for which no sentence is quoted: cancer (1 paper); glioma (1); head and neck squamous cell carcinoma (1); pachyonychia congenita (1); prostate carcinoma (1); psoriasis vulgaris (1); skin carcinoma (1); tumor (1).